RN7SL419P (RNA, 7SL, cytoplasmic 419, pseudogene)
Gene: Miscellaneous RNA gene on chromosome 4 (153,381,729 to 153,382,015, reverse strand). Ensembl gene ENSG00000243883.
Homologues: Orthologues: chimpanzee Metazoa_SRP (100% identical), macaque Metazoa_SRP (93% identical), dog Metazoa_SRP (74% identical). Paralogues in human: RN7SL1 (83% identical), RN7SL2 (83% identical), RN7SL3 (82% identical), Metazoa_SRP (81% identical), RN7SL627P (81% identical), RN7SL220P (81% identical), RN7SL709P (81% identical), RN7SL788P (81% identical), RN7SL296P (80% identical), RN7SL186P (80% identical), RN7SL18P (80% identical), RN7SL300P (80% identical), and 703 more.